ALDH1A1 (aldehyde dehydrogenase 1 family member A1)
Description:
Cytosolic dehydrogenase that catalyzes the irreversible oxidation of a wide range of aldehydes to their corresponding carboxylic acid. Functions downstream of retinol dehydrogenases and catalyzes the oxidation of retinaldehyde into retinoic acid, the second step in the oxidation of retinol/vitamin A into retinoic acid. This pathway is crucial to control the levels of retinol and retinoic acid, two important molecules which excess can be teratogenic and cytotoxic. Also oxidizes aldehydes resulting from lipid peroxidation like (E)-4-hydroxynon-2-enal/HNE, malonaldehyde and hexanal that form protein adducts and are highly cytotoxic. By participating for instance to the clearance of (E)-4-hydroxynon-2-enal/HNE in the lens epithelium prevents the formation of HNE-protein adducts and lens opacification. Also functions downstream of fructosamine-3-kinase in the fructosamine degradation pathway by catalyzing the oxidation of 3-deoxyglucosone, the carbohydrate product of fructosamine 3-phosphate decomposition, which is itself a potent glycating agent that may react with lysine and arginine side-chains of proteins. Also has an aminobutyraldehyde dehydrogenase activity and is probably part of an alternative pathway for the biosynthesis of GABA/4-aminobutanoate in midbrain, thereby playing a role in GABAergic synaptic transmission (By similarity).
Synonyms: RalDH1; ALDC; ALDH1; PUMB1; ALDH-E1; ALDH11; HEL-9; HEL-S-53e; HEL12
Tractability: Small molecule: a structure with a bound ligand is known; a high-quality ligand is known; it belongs to a druggable protein family. PROTAC: ubiquitination databases record sites on it; its protein half-life has been measured; a small molecule that binds it is known.
Target class: Enzyme; Oxidoreductase
Chemical probes: NCT-505 (high quality), PD134680
Safety:
Unwanted effects reported when the protein is acted on. In parentheses: how it was acted on, where the effect was seen, and who reports it.
Drug Toxicity (source: ClinPGx)
Gene: Protein-coding gene on chromosome 9 (72,900,670 to 73,080,442, reverse strand). Ensembl gene ENSG00000165092.
Subcellular location: Cytoplasm, cytosol; Cell projection, axon
Subcellular location (Human Protein Atlas): Cytosol
Pathways (Reactome):
Developmental Biology: Developmental Lineage of Mammary Gland Luminal Epithelial Cells; Developmental Lineage of Mammary Gland Myoepithelial Cells; Developmental Lineage of Mammary Stem Cells
Metabolism: Ethanol oxidation; Fructose catabolism
Signal Transduction: RA biosynthesis pathway
Gene Ontology:
Molecular function: 3-deoxyglucosone dehydrogenase activity; acetaldehyde dehydrogenase (NAD+) activity; aldehyde dehydrogenase (NAD+) activity; benzaldehyde dehydrogenase (NAD+) activity; NAD+ binding; protein binding; aminobutyraldehyde dehydrogenase (NAD+) activity; androgen binding; GTPase activator activity; NAD binding; retinal dehydrogenase (NAD+) activity; medium-chain fatty aldehyde dehydrogenase (NAD+) activity; oxidoreductase activity
Biological process: cellular detoxification of aldehyde; fructosamine catabolic process; 9-cis-retinoic acid biosynthetic process; aldehyde metabolic process; gamma-aminobutyrate shunt; maintenance of lens transparency; negative regulation of cold-induced thermogenesis; retinoid metabolic process; retinol metabolic process
Cellular component: cytosol; extracellular exosome; mucus layer; axon; cytoplasm; synapse
Genetic constraint (gnomAD): Loss-of-function variants: 17 observed, 47.07 expected, observed/expected ratio (o/e) 0.36, 90% interval 0.25 to 0.54. The upper end of that interval is the gene's LOEUF score, 0.54, which puts it in group 2 of 6, group 1 being the genes least tolerant of losing a copy. Missense variants: 434 observed, 531.58 expected, observed/expected ratio (o/e) 0.82, 90% interval 0.75 to 0.88. Synonymous variants: 190 observed, 192 expected, observed/expected ratio (o/e) 0.99, 90% interval 0.88 to 1.12.
Homologues: Orthologues: chimpanzee ALDH1A1 (100% identical), macaque ALDH1A1 (96% identical), pig ALDH1A1 (92% identical), dog ALDH1A1 (89% identical), mouse Aldh1a1 (87% identical), rat Aldh1a1 (86% identical), mouse Aldh1a7 (84% identical), rabbit ALDH1A1 (84% identical), tropical clawed frog aldh1a1 (78% identical), rat Aldh1a7 (77% identical), Caenorhabditis elegans alh-1 (63% identical), Caenorhabditis elegans alh-2 (60% identical), and 3 more. Paralogues in human: ALDH1A2 (73% identical), ALDH1A3 (70% identical), ALDH2 (68% identical), ALDH1B1 (64% identical), ALDH1L1 (50% identical), ALDH1L2 (49% identical), ALDH9A1 (39% identical), ALDH8A1 (36% identical), ALDH5A1 (34% identical), ALDH6A1 (31% identical), ALDH7A1 (30% identical), ALDH4A1 (28% identical), and 5 more.
Diseases named in the same sentence as ALDH1A1 in open-access papers:
ALDH1A1 is named in the same sentence as 292 diseases in open-access papers, as found by Europe PMC text mining. Sharing a sentence is not in itself a finding about the gene and the disease. The quoted sentences say what the papers report.
breast carcinoma (517 papers, 2008 to 2025). "In breast cancer, ALDH1A1 has been implicated in the acquisition of drug resistance, associated with poor prognosis." (PMID 40781130, 2025). "ALDH1A1 is a major BCSC biomarker associated with significantly lower overall survival in parallel with FAK overexpression in breast cancer patients." (PMID 37185776, 2023). "ALDH1A1 has recently been linked to the prognosis of several human cancers, including breast cancer, lung cancer, ovarian cancer, and esophageal cancer." (PMID 37359050, 2023). "ALDH1A3 overexpression significantly increased ALDEFLUOR activity in MDA-MB-231 breast cancer cells, and the increase was greater than that caused by ALDH1A1 overexpression." (PMID 36651035, 2023). "Elevated ALDH1A1 expression has been associated with breast cancer stem cells (CSCs), which contribute to tumor initiation, progression, and metastasis." (PMID 37176102, 2023). "Acetylation of ALDH1A1 at K353 by p300/CBP-associated factor (PCAF) inhibits the CSCs population as well as self-renewal property of breast cancer." (PMID 35216622, 2022). "ALDH1A1 and ALDH1A3 can dramatically enhance ALDH1 activity and are associated with a poor prognosis in patients with breast cancer." (PMID 36387165, 2022). "We examined a handful of CSC markers commonly associated with breast cancer (ALDH1A1, ABCG2, PGP, FUT4)." (PMID 34579762, 2021). "ALDH1A1 expression in breast cancer has also been associated with advanced disease stages, triple negative cells, and poor prognosis." (PMID 35582039, 2020). "In 882 breast cancer patients treated with cyclophosphamide and doxorubicin, two SNPs of ALDH1A1 associated with an increased risk of hematological toxicity, grades 3 and 4, have been discovered." (PMID 35582039, 2020). "The mechanism underlying tumor aggressiveness promoted by ALDH1A1 expression in certain breast cancer phenotypes remains poorly defined." (PMID 30541574, 2018). "Since TAZ is also involved in the formation of CSC in other cancers such as breast cancer, our findings provide the first molecular mechanism underlying enhanced levels of Aldh1a1 in CSCs." (PMID 28415606, 2017). "Results from these three independent studies demonstrated that high ALDH1A1 gene expression level is associated with reduced breast cancer recurrence and total mortality in patients with TNBC, independent of age at diagnosis and TNM stage." (PMID 26462023, 2015). "The overall and subcategory analyses were performed to detect the association between ALDH1A1 expression and clinicopathological/prognostic parameters in breast cancer patients." (PMID 24938375, 2014). "Additionally, several single-nucleotide polymorphisms (SNPs) in ALDH1A1 have been linked to an increased risk of breast cancer mortality." (PMID 39781359, 2025). "Importantly, ALDH1A1 has been implicated in lowering intracellular pH in breast cancer cells, suppressing antitumor immunity, and thereby fostering cancer progression." (PMID 39107297, 2024). "High ALDH1A1 activity was associated with a poor prognosis for breast cancer patients." (PMID 36651035, 2023). "hypothesized that in breast cancer cells, ALDH1A1 overexpression was associated with either a better or a worse prognosis, depending on the cut-off." (PMID 35814382, 2022). "Interestingly, it was shown that expression of ALDH1A1 was also associated with HIF-2α expression in breast cancer cell lines and samples." (PMID 36139678, 2022).
breast carcinoma (continued). "Furthermore, expression of ALDH1A1, a breast cancer-specific stem cell marker associated with resistance to some chemotherapies, was elevated." (PMID 34579762, 2021). "Furthermore, ALDH1A1-positive breast cancer cells are suggested to be associated with a more aggressive phenotype of CSCs from a higher tumour grade." (PMID 31728117, 2019). "ALDH1A1 can inactivate integral agents of chemotherapy; therefore, it has been postulated that breast cancer patients with high ALDH1A1 expression may have an increased risk of recurrence." (PMID 26462023, 2015). "Because breast cancer stem cells have been implicated in radiation and chemotherapy resistance, as well as increasing the potential for metastasis, our finding of ALDH1A1 in TNBC may explain the more frequent relapse in TNBC patients." (PMID 22110952, 2011). "In conclusion, ALDH1A1 might be associated to progression and diffusion of breast cancer." (PMID 30541574, 2018). "Studies have confirmed that MUC1-C induces ERK signaling and thereby phosphorylation and activation of C/EBPβ, and show that a complex of MUC1-C and C/EBPβ occupies the ALDH1A1 promoter and induces ALDH1A1 expression, promotes breast cancer progression." (PMID 40708788, 2025). "ALDH1A1 has been shown to influence the immune microenvironment in breast cancer by promoting the expansion of myeloid-derived suppressor cells that facilitate tumor progression." (PMID 39781359, 2025). "ALDH1A1 and ALDH1A3 both drive retinoic acid production in breast cancer, and have been linked to angiogenesis, tumor invasion, and metastasis." (PMID 40076923, 2025). "ALDH1A1 is best known as a marker of breast cancer stem cells, primarily through catalyzing the oxidation of retinaldehyde to retinoic acid—a key regulator of cellular differentiation." (PMID 40076923, 2025). "Mechanistically, ALDH1A1 decreased the intracellular pH in breast cancer cells to promote phosphorylation of TAK1, activate NF-κB signaling, and increase the secretion of GM-CSF, which led to myeloid-derived suppressor cell expansion and immunosuppression." (PMID 40708788, 2025). "We and others have shown that ALDH1A1 is upregulated in response to radiation in SUM159 as well as other claudin low breast cancer cell lines." (PMID 40076923, 2025). "The metabolic enzyme aldehyde dehydrogenase 1A1 (ALDH1A1), a cancer stem cell marker associated with poor outcomes in breast cancer, has emerged as a promising therapeutic target in TNBC." (PMID 40076923, 2025). "ALDH1A1 expression in breast cancer is correlated estrogen receptor negativity, high grade, tumor size and stage, lymph node metastasis, and drug resistance." (PMID 40076923, 2025). "Most of the work relating to Aldh expression and breast cancer centres on Aldh1A1 as a stem cell marker." (PMID 40781130, 2025). "The activity of ALDH1A1 in tumor-initiating cells can lower the intracellular pH of breast cancer cells, promote the phosphorylation of TAK1, activate NF-kB signaling, and increase the secretion of GM-CSF." (PMID 41368628, 2025). "The ALDEFLUORTM kit used to isolate CSCs in this study has previously been shown to select cells expressing high levels of ALDH1A1, ALDH3A1, ALDH1A3 and ALDH2 isoforms, which are closely linked to breast cancer stem cells." (PMID 39768151, 2024). "The phytochemical downregulates the activity of aldehyde dehydrogenase 1A1 (ALDH1A1), an enzyme whose high expression level corresponds to the increased clonogenicity, tumorigenicity, invasiveness, and stemness properties of breast cancer." (PMID 38543147, 2024). "We investigated the associations of reproductive factors known to influence breast cancer risk with the expression of breast stem cell markers CD44, CD24, and ALDH1A1 in benign breast biopsy samples." (PMID 38577336, 2024). "The present study focused on inducing oxidative stress, which triggers ferroptosis via ferritin degradation in ALDH1A1 oral and breast cancer stem cells." (PMID 39513121, 2024).
breast carcinoma (continued). "In breast cancer, elevated ALDH1 expressions, particularly ALDH1A1 and ALDH1A3, are associated with chemoresistance, particularly cyclophosphamide-based regimens." (PMID 39796106, 2024). "The METABRIC data cohort identified a significant correlation between overexpression of CD44/ALDH1A1 and HSP90 or HSF1 in patients with HER2-positive breast cancer, which was associated with relatively poorer overall survival." (PMID 38646654, 2024). "On the other hand, NOTCH signaling promotes breast cancer stem cells by activating ALDH1A1 through the induction of SIRT2, which results in ALDH1A1 deacetylation and enzyme activation." (PMID 39479446, 2024). "The prognostic significance of ALDH1A1 for breast cancer continues to be a subject of controversy, notwithstanding the existence of numerous independent investigations." (PMID 39204369, 2024). "Among the members of the ALDH1 family, ALDH1A1 and ALDH1A3 have a much more dominant role in upregulating ALDH1 activity, potentially resulting in a poor prognosis in breast cancer." (PMID 39796106, 2024). "A recent meta-analysis identified ALDH1A1 as a biomarker for predicting tumor growth and poor survival in breast cancer patients." (PMID 39204369, 2024). "Stemness marker ALDH1A1 increased tumor angiogenesis in MCF-7 breast cancer cells via retinoic acid/HIF-1/VEGF signaling." (PMID 36675306, 2023). "IHC analysis of another group containing 69 breast cancer samples yielded similar results, showing that 20.3% (14/69) of the samples expressed ALDH1A1, and breast cancer cells strongly positive for ALDH1A1 represented only 4.3% of the 14 positive samples." (PMID 36651035, 2023). "Kaplan–Meier curves revealed that the overall survival of breast cancer patients with the high expression of ALDH1A1 and FAK, shorter survival was observed (log-rank test, p = 0.0187)." (PMID 37185776, 2023). "ALDH1A1 expression in breast cancers generates a favorable microenvironment by increasing angiogenesis through a retinoic-acid-dependent mechanism." (PMID 36675306, 2023). "Our results further confirm the low expression of CD24, high expression of ALDH1A1 and stem cell self-renew genes in B7-H4-KO breast cancer cells." (PMID 37794509, 2023). "In several studies in other cancer types, including breast cancer, stromal ALDH1A1 protein level, as measured by immunohistochemistry, was associated with better clinical outcomes." (PMID 37628927, 2023). "Consistent with breast cancer, ALDH1A1‐positive PCa and lung cancer cells display higher colony formation ability and sphere formation efficiency in vitro as well as greatly tumorigenic potential in vivo than ALDH1A1‐negative cells." (PMID 36694633, 2023). "According to a previous in silico research, the ellipticine reactive metabolites 13-hydroxyellipticine and 12-hydroxyellipticine are likely to be effective drugs for treating breast cancers with strong ALDH1A1 activity." (PMID 37359050, 2023). "ALDH1A1+ breast cancer cells exhibit a more aggressive phenotype, increased migration, invasion, and resistance to chemotherapy." (PMID 37176102, 2023). "The IHC results of tissue arrays of 481 breast cancer samples indicated that 26% of the samples expressed ALDH1A1, and ALDH1A1+ breast cancer cells accounted for approximately 5% of the total cells." (PMID 36651035, 2023). "SIX1 showed a significant positive correlation with breast cancer stem cell markers such as ALDH1A1, EPCAM, ITGB1, and SOX2." (PMID 38031089, 2023). "In breast cancer cells, knockdown of ALDH1A1 increased the sensitivity to chemotherapy and radiotherapy." (PMID 37954205, 2023). "Sirtuin 2 (SIRT2) is induced via the NOTCH signaling pathway to deacetylate aldehyde dehydrogenase A1 (ALDH1A1) at K353 leading to the increase of its enzyme activity and the promotion of breast cancer stem cells (CSCs) properties." (PMID 35216622, 2022).